TNF (tumor necrosis factor)
Diseases named in the same sentence as TNF in open-access papers (continued):
Sharing a sentence is not in itself a finding about the gene and the disease.
breast tumor (continued). "In our published studies we demonstrated that the exposure of Luminal-A breast tumor cells to combined “TME Stimulation” by estrogen+TNFα+EGF for three days in culture had driven a high in vivo metastatic phenotype in Luminal-A breast tumor cells." (PMID 27835603, 2016). "TNFα cooperates with Ras in promoting the metastatic phenotype of MCF-7 breast tumor cells, and turns WT-Ras into a tumor-supporting entity." (PMID 24598028, 2014). "Obviously, extensive research is needed in order to assess the impact of TNFα inhibitors on breast tumor cells both in vitro and in vivo, and to design the proper clinical administration mode." (PMID 24369447, 2013). "In particular, interleukin-6 (IL-6) and tumor necrosis factor-alpha (TNF-α) have been reported to be elevated in the blood serum of patients diagnosed with advanced stage breast tumor and correlate with an increased number and size of metastatic sites." (PMID 23372803, 2013). "In mammospheres exposed to the breast tumor fibroblasts supernatant, autocrine tumor necrosis factor-α signalling engenders the functional interplay between peroxisome proliferator activated receptor-α and hypoxia inducible factor-1α (PPARα/HIF1α)." (PMID 23372804, 2013). "Overall, our findings indicate that TNFα induces many metastasis-related functions in luminal breast tumor cells and that its activities are largely amplified by cooperativity with estrogen and EGF." (PMID 24369447, 2013). "This “combined stimulation” by TNFα + Estrogen + EGF provides a more relevant representation of the multifaceted nature of the tumor microenvironment in luminal breast tumors than the reductionist approach of testing the activity of each element alone." (PMID 24369447, 2013). "Infiltration of these tumor-promoting immune cells as well as various inflammatory cytokines, particularly TNF-α and IL-6, has been found in the breast tumor microenvironment." (PMID 23372803, 2013). "Due to its proapoptotic activity, TNF-α can inhibit in vitro growth of some tumor cells including breast tumor cell lines." (PMID 22235273, 2012). "While the expression of CCL2, CCL5, TNFα or IL-1β was only minimally detected in infiltrating leukocytes of all groups of patients, the four factors were clearly observed in breast tumor cells, with mainly a cytoplasmic staining pattern." (PMID 21486440, 2011). "A large body of reports demonstrated the stimulatory role for TNF-α, IL-1 and IL-6 in the proliferation of breast tumors." (PMID 21209958, 2010). "It is worth to note that TNF-α acts as a mediator of the apoptotic process and has selective cytotoxicity against malignant breast tumor cells, promoting an apoptotic type of cell death in MCF-7 cells." (PMID 16504042, 2006). "Additionally, evidence suggests that TNF-α contributes to the inflammatory setup of breast tumors and enhances tumor activity." (PMID 40430573, 2025). "In this study, we aimed to address whether TGF-β and TNF-α, two proinflammatory factors frequently detected in tumor niches, impact neutrophil recruitment to breast tumors." (PMID 40833805, 2025). "These structures release pro-inflammatory factors, including interleukins (IL-6, IL-8), monocyte chemotactic protein (MCP-1), and tumor necrosis factor alpha (TNFα), which promote a pro-inflammatory environment in the breast tumor microenvironment, thereby facilitating the development of BC." (PMID 40165893, 2025). "Inhibition of TNF-α is protective against chemically induced breast tumors." (PMID 39175950, 2024). "TNF-α, which is highly expressed in breast tumors, is released by tumor cells in response to LPS." (PMID 39175950, 2024). "Pro-inflammatory mediators such as TNF-α and IL-6 are key players in cancer-related inflammation, and inhibition of these cytokines could protect against chemically induced breast tumors." (PMID 38818375, 2024).
breast tumor (continued). "Taken together, this study highlights the role of TNF-α-induced NF-κB activation in regulating inflammatory signaling and explores new molecular insights that can attenuate the invasiveness and metastatic properties of breast tumors." (PMID 38201482, 2023). "High concentrations of serum inflammatory factors [tumor necrosis factor-α (TNF-α), transforming growth factor β (TGF-β)], and reduced total antioxidant capacity (TAC) are important risk factors for the development and progression of breast tumors." (PMID 38023986, 2023). "During the in vitro conversion process of mesenchymal stromal cells in cancer-associated fibroblast by breast tumor cell (MDA-MB-231 and MCF-7)-conditioned media, TNF-alpha stimulation is responsible for the chemokines released (CCL2, CXCL8, and CCL5) by the tumor stromal cells." (PMID 37681908, 2023). "As already described, TNFα and IL-1β are involved in various pathological processes, such as chronic inflammation, autoimmunity, and cancer, and both cytokines are highly relevant to the inflammatory condition of breast tumors." (PMID 37208442, 2023). "Thus, these combined results show that blocking TNF-α activity in vivo decreased the expression of ATX in primary breast tumors." (PMID 38201482, 2023). "Exposure of rat- and human-derived adipose tissue to γ-radiation produces a significant inflammatory response, and inflammatory cytokines secreted by breast tumors, including IL-1β, IL-6, IL-10, and TNF-α, stimulate ATX secretion by activating the NF-κB pathway." (PMID 36880535, 2023). "We found that the TNF signaling pathway was significantly upregulated, whereas nitrogen metabolism, propanoate metabolism, and aminoacyl-tRNA biosynthesis were significantly downregulated in breast tumors." (PMID 35898399, 2022). "Hence, TNF-α modulates flux of NADH which will shift the TCA cycle intermediates towards anaplerotic reactions in aggressive breast tumor cells (MDA-MB-231)." (PMID 33926547, 2021). "Moreover, TNF-α is strongly correlated with inflammation in breast tumors, and an increase in its expression is strongly correlated with relapse and advanced disease." (PMID 33150070, 2020). "Finally, its association with inflammatory factors such as COX2, IL-6 and TNFα provides further evidence that AIF1v1 is a key regulator of inflammation in the breast tumor microenvironment and interacts with a wide variety of cytokines and adipokines." (PMID 30386176, 2018). "Similarly a significant increase in CD47 expression was observed in three out of four PDX breast tumour samples (PDX1 showing the greatest effect) and one primary patient breast tumour after treating the cells with TNF-α for 24 h." (PMID 28378740, 2017). "TNFα and TGFβ1 are both expressed in many tumors and, as our findings so far indicate, act in cooperativity to promote the pro-inflammatory phenotype of MSCs, which also prevail in breast tumors." (PMID 28553282, 2017). "However, it is interesting to note that LPS-RS (Lipid IVA) suppressed TNF-α production in breast tumor cells treated with LPS, but in the same cell line potentiated TNF-α release in the presence of docetaxel." (PMID 28915246, 2017). "Following stimulation of the MSCs for 24 h by TNFα + TGFβ1 or by their vehicles, the CM of cytokine-stimulated or of vehicle-exposed cells (Groups 4 and 3, respectively) were transferred to mCherry-expressing breast tumor cells." (PMID 28553282, 2017). "Viana have revealed that 4T1 tumor bearing mice showed higher levels of MCP-1, VEGF, and TNF-α in serum compared to controls, suggesting that these mediators might respond to breast tumor growth." (PMID 27983683, 2016). "Indeed, in this study we demonstrate that the combined TME Stimulation by estrogen+TNFα+EGF has enriched Luminal-A breast tumor cells not only for the CD44+/β1+ sub-population, but also for the CD44+/CD24low/− sub-population." (PMID 27835603, 2016). "TNF-α and IL-1β are highly relevant to the inflammatory setup of breast tumors." (PMID 25928089, 2015).
breast tumor (continued). "Furthermore, the chronic expression of TNF-α in breast tumors has been demonstrated to be correlated with lymph node involvement, suggesting the role of TNF-α in enhancing tumor cell metastasis." (PMID 25010932, 2014). "Such a cross-talk may lead to up-regulated expression of CCL2 and CCL5 in tumors expressing TNFα and/or IL-1β, thus possibly leading to increased tumor-supporting activities of the two chemokines in breast tumors (see Discussion, below)." (PMID 21486440, 2011). "The inter-connection between CCL2 & CCL5 and TNFα & IL-1β in the immune setting suggests that similar interactions exist between these chemokines and cytokines also within the inflammatory context of breast tumors." (PMID 21486440, 2011). "Moreover, since TNF-α is highly expressed in tumors, we further applied the NF-κB gene signature documented in TNFα-stimulated endothelial cells to human breast tumors." (PMID 21754991, 2011). "Indeed, the collaboration of PDGF signalling and TNF have long been known to be required for tissue repairing, and their abnormal expression play important but partially defined roles in breast tumor development and progression." (PMID 18366601, 2008). "Besides, in the human breast tumor derived cell line MCF-7 the synthetic GC dexamethasone (Dex) is able to completely abrogate the TNF-α-mediated cell death." (PMID 16504042, 2006). "The suppression of TNF-α may protect against chemically induced breast tumors." (PMID 40430573, 2025). "RT to the intact breast tumors produces inflammatory cytokines such as TNF-α, IFN-γ which can promote neutrophil differentiation towards the N1 antitumor phenotype, which might explain why more pretreatment neutrophils can be favorable for tumor elimination by a NACRT." (PMID 37046691, 2023). "Our data may have implications with regard to interaction between breast tumor cells and their microenvironment, as the biologically relevant concentrations of TNF-α in the tumor microenvironment may lead to enhanced/sustained expression of IP-10 by the tumor cells." (PMID 34572567, 2021). "Published studies have shown that pDCs infiltrate breast tumors, but are impaired by TGF-β and TNF-α to produce IFN-α, and associated with poor clinical prognosis, indicating that pDCs might contribute to the immune escape of breast tumors and ultimately promote their growth." (PMID 34737750, 2021). "In addition, pDCs-derived TNF-α in breast tumors triggered activation of the NF-κB signaling pathway in cancer cells, which in turn upregulated the expression level of CXCR4 and led to increased metastasis to lymph nodes, which ultimately promoted cancer progression." (PMID 34737750, 2021). "Making use of shRNA to TNFα and the N-terminal fragment of tmTNFα, the authors of this investigation have concluded that reduced expression of tmTNFα improved the sensitivity of breast tumor cells to doxorubicin, and that the activities of tmTNFα in resistance were meditated by NF-κB and Erk." (PMID 33585241, 2020). "It was also revealed that the combined chemo-MF therpay, combined chemo-PTT, and combined chemo-MF-PTT - based on Lf-Doxo-PMNSs could significantly reduce the volume and size of breast tumor, by inducing extrinsic (TNF-α) and intrinsic (Bax) pathways of the apoptosis." (PMID 32245980, 2020). "Additionally, the higher serum levels of the pro-inflammatory cytokine TNF-α may contribute to the increased tumor cell survival and PD-L1 stabilization on breast tumor cells, playing a critical role for tumor escape from immune surveillance." (PMID 32481540, 2020). "Reduced levels of activation-associated cytokines (IL-2, TNF-α, IFN-γ) are an important characteristic of exhausted T cells, and we report that the levels of these cytokines in CD8+ T cells isolated from spleens of mice-bearing mouse 4T1 breast tumours are, as expected, similarly reduced." (PMID 31594465, 2019).
breast tumor (continued). "Furthermore, breast tumors that overexpress AGR2 exhibit downregulation of KEGG pathways epitomized by the inflammatory response, including Pathogenic Escherichia Coli infection, HTLV-1 infection, and TNF pathway." (PMID 29796176, 2018). "Therefore, being highly expressed in breast tumors, TNFα may “bring the evil” out of WT-Ras and these two components together may lead to intensified pro-malignant effects that are deleterious in terms of angiogenesis and tumor progression." (PMID 24598028, 2014). "First, we explored cancer databases and established that TNF-α, RELA and ATX in breast tumors showed positive correlations in patients." (PMID 38201482, 2023). "The combination of anti-TNF-α and anti-IFN-γ blocking antibodies reversed the tumor-suppressing effect of TSLP induction and resulted in an accelerated breast tumor growth compared with IgG-treated group (p < 0.0001)." (PMID 36467403, 2022). "Our data demonstrated MMP-7 activation in human epithelial cells after treatment with IL-1β or TNFα and are supported by publications showing that MMP-7 is secreted by colon and breast tumors, which are primarily epithelial cells." (PMID 36275703, 2022). "Organotypic cultures of primary human breast tumors and patient-derived xenografts sensitive to paclitaxel exhibit gene expression signatures typical of type I IFN and TNFα exposure." (PMID 31937780, 2020). "The sensitivity of our assays is highlighted by the reproducible detection of TNF-α-induced RIPK1 activation and the detection of 46 T-loop phosphorylation sites from a breast tumor needle biopsy." (PMID 31521607, 2019). "Expression levels of multiple cytokines were higher in ER- compared to ER+ breast tumors, including IFN-γ, TNF-α, and IL-6 and IL-8." (PMID 28899409, 2017). "TNF-α can also stimulate cell death pathways in tumors, as docetaxel-induced TNF-α production was shown to be cytotoxic in breast tumor cells via autocrine signaling." (PMID 28915246, 2017). "Using the joint powers of the TNFα + Estrogen + EGF stimulation, we found that MCF-7 luminal breast tumor cells have acquired very high metastasis-related functions." (PMID 24369447, 2013). "In our study, we have compared side by side the ability of TNFα, estrogen, and/or EGF to affect spreading and EMT properties, using the MCF-7 luminal breast tumor cells." (PMID 24369447, 2013). "TNFα, estrogen, and EGF were each shown to have the potential to promote metastasis-related properties in breast tumor cells; however, different research systems were used for the study of each of these factors." (PMID 24369447, 2013). "Above, we have shown that the combined stimulation by TNFα + Estrogen + EGF has strongly induced spreading and EMT properties in luminal breast tumor cells." (PMID 24369447, 2013). "In primary breast tumor and metastatic sites, TRAIL is released by BC cells, activated fibroblasts, macrophages, lymphocytes and post- TNF-α/interferon-α/-γ stimulated mesenchymal stem cells (MSCs)." (PMID 22709548, 2012). "This lack of coordination between CCL2 & CCL5 and TNFα & IL-1β in this sub-population is intriguing mainly because TNFα and IL-1β were found to stimulate the release of CCL2 and CCL5 by breast tumor cells." (PMID 21486440, 2011). "Yet, how the combined action of TGF-β1 and TNF-α controls the secretion of neutrophil guidance cues in breast tumors has not been studied." (PMID 40833805, 2025). "Besides, hypoxia can induce the upregulation of TET1 and TET3 in breast tumor–initiating cells (BTIC), which is required to activate TNFα–p38–MAPK signaling that drives breast tumor malignancy." (PMID 38468288, 2024). "Our team has shown that the regression of transplanted Polyoma Virus middle T antigen (PyMT) breast tumors by STING agonist treatment also relies on an initial burst of cytokines and chemokines released by TAMs, in particular, Type-I interferon (IFN) and Tumor necrosis factor α (TNFα)." (PMID 35884605, 2022).
breast tumor (continued). "We did not detect IL1β mRNA in the MCF7 or T47D breast tumor cell lines, whereas TGFβ and TNFα were detected in these cells, highlighting a potential paracrine effect of these two effectors on breast APCs." (PMID 36009475, 2022). "Since IP-10 induction by TNF-α in breast tumor cells has yet not been studied, we sought to determine the impact of TNF-α stimulation on the regulation of IP-10 expression in MCF-7 cells." (PMID 34572567, 2021). "Yet, the impact of persistent proinflammatory stimulation on breast tumor cells was not investigated in depth, leading us to determine the effects of continuous TNFα + IL-1β stimulation on TNBC cell characteristics and functions." (PMID 34072893, 2021). "In the same spirit, in response to CM of blood monocyte-derived macrophages, several breast tumor cell lines acquired a stronger invasive capability; in MCF-7 cells, this effect was mediated by TNFα-induced stabilization of snail, mediated by the ability of the cytokine to activate NF-κB." (PMID 33585241, 2020). "The mRNA expression of IL-6 was upregulated by 3-fold in breast tumor cells when co-cultured with adipocytes, whereas both IL-1β and TNFα were not obviously affected." (PMID 30013512, 2018). "IL1B, IL6, TNF, IL8 and CXCR4 mRNA levels were significantly increased in the high AHR-expressing ERα-negative breast tumor subpopulation, while these associations were only observed for IL6 and CSF1 in the ERα-positive tumor subgroup." (PMID 29320557, 2018). "Finally, lower levels of several pro-inflammatory cytokines (IL1B, IL10, IL12, IL6, IL8, TNF), NK cell metagenes (NCR1, XCL1), cytolytic enzymes (GZMA, GZMB, PRF) and type I IFN-induced genes were also observed in IL-1R8 high breast tumors." (PMID 28533483, 2017). "Together, these findings suggest that tumors containing high levels of TNFα and TGFβ1 are enriched with the inflammatory and tumor-promoting mediators CCL2, CXCL8 and Cox-2, and that all three inflammatory mediators are coregulated in human breast tumors." (PMID 28553282, 2017). "Among patients with RA and a history of breast neoplasm, those who started a TNF-α-inhibitor treatment did not experience more breast neoplasm recurrences than patients with RA treated otherwise." (PMID 26253105, 2015). "Exposure of MSCs to TNF-α led to potent CCL2-induced migration of monocytic cells, a process that may yield pro-cancerous myeloid infiltrates in breast tumors." (PMID 25928089, 2015). "Our findings have shown that as a result of the combined stimulation by TNFα + Estrogen + EGF, luminal breast tumor cells have gained an extensive spreading phenotype in which Src activation has given rise to tumor cell spreading and to localization of FAK and paxillin in tumor cell protrusions." (PMID 24369447, 2013). "In view of the multi-factorial nature of the tumor microenvironment, in this study we determined the combined impact of the three arms—inflammatory (TNFα) + hormonal (estrogen) + growth-supporting (EGF)—on malignancy-promoting characteristics and functions of luminal breast tumor cells." (PMID 24369447, 2013). "We observed a positive correlation between TNF and 16 (84.2 %) of the 19 endothelial TNF-α-inducible genes in both ERα-negative and ERα-positive breast tumors." (PMID 21754991, 2011). "Relationship between expression of TNF and expression of the 19 others identified putative TNF-inducible genes in 48 REα negative breast tumors and 48 REα positive breast tumors." (PMID 21754991, 2011). "Indeed, our findings and published studies indicate that TNFα and IL-1β up-regulate the release of CCL2 and CCL5 by breast tumor cells." (PMID 21486440, 2011). "We found a significant positive correlation between TNF and the majority (85 %) of the identified endothelial TNF-induced genes in a well-defined series of 96 (48 ERα positive and 48 ERα negative) breast tumors." (PMID 21754991, 2011).